LARGE-IT1 (LARGE intronic transcript 1)
Gene: Long non-coding RNA gene on chromosome 22 (33,723,832 to 33,724,912, reverse strand). Ensembl gene ENSG00000232081.
Diseases named in the same sentence as LARGE-IT1 in open-access papers:
LARGE-IT1 is named in the same sentence as 1 disease in open-access papers, as found by Europe PMC text mining. Sharing a sentence is not in itself a finding about the gene and the disease.
glioblastoma (1 paper, 2023). The most malignant astrocytic tumor (WHO grade IV).